JAK2 (Janus kinase 2)
Diseases named in the same sentence as JAK2 in open-access papers (continued):
Sharing a sentence is not in itself a finding about the gene and the disease.
hematologic malignancies (continued). "For example, the JAK2 V617F mutation has been detected in elderly individuals who do not exhibit clear signs of an MPN, but who have increased risk of developing a subsequent hematologic malignancy and cardiovascular mortality." (PMID 38338802, 2024). "Mutations in Jak2 are associated with blood disorders and knockout mice are not viable due to the effects on hematopoiesis." (PMID 37367478, 2023). "Clinical studies of type-I JAK2 inhibitors in hematological malignancies and their specificities." (PMID 35903543, 2022). "The JAK2 V617F mutation can also be frequently detected in the peripheral blood of healthy individuals who do not yet have symptoms of hematological disease." (PMID 33661998, 2021). "Currently, combinations strategies that include IFN-α/β appear to be the most promising immunomodulating approaches for the treatment of hematologic malignancies, such as those combining JAK2 inhibitors with IFN-α/β for MPN, with a real possibility of inducing long-term remissions." (PMID 29181334, 2017). "The specialist consultation done in 2012 excluded the presence of any unrecognised haematological disorder (the patient was negative for the JAK-2 mutation), and recommended watchful waiting." (PMID 26911866, 2016). "As a result, several JAK2 inhibitors have entered clinical trials for hematologic malignancies." (PMID 24830942, 2014). "In addition, it has been highly efficacious in three mouse models of Jak2-mediated hematological disease." (PMID 25162558, 2014). "As a result, resveratrol may have therapeutic potential against not only NK neoplasms but also haematological disorders where dysregulated JAK2 signaling plays a critical role in pathogenesis." (PMID 23372833, 2013). "Various fusions with JAK2 have been reported in hematological malignancies." (PMID 23716474, 2013). "Our data suggest that perturbing JAK2 activation may have unexpected consequences in elevation of platelet number and correspondingly, important implications for treatment of hematological disorders with constitutive Jak2 activity." (PMID 24086539, 2013). "The JAK family includes JAK1, JAK2, JAK3, and Tyk2, and their inhibition is known to be therapeutic for many autoimmune and hematological diseases." (PMID 39742289, 2024). "Other potential predictive factors that have been reported in patients with hematologic malignancies include age, use of BCL2 inhibitors, use of JAK2 inhibitors, absolute lymphocyte count, and circulating CD4+, CD8+, and natural killer cell counts." (PMID 37685720, 2023). "Previously published data have demonstrated that JAK2‐V617F‐positive MPN cells display PD‐L1, a major immune checkpoint antigen mediating immunological resistance in neoplastic cells in diverse hematologic malignancies." (PMID 35015307, 2022). "Small molecule inhibitors targeting cellular oncoproteins and enzymes such as BCR-ABL, JAK2, Bruton tyrosine kinase, FLT3, BCL-2, IDH1, IDH2, are biomarker-driven chemotherapy-free agents approved for several major hematological malignancies." (PMID 33879198, 2021). "The JAK2/STAT3 axis is one of the most recognized signaling pathway, whose constitutive activation occurs with high frequency in several hematopoietic diseases and solid tumors." (PMID 31817171, 2019). "Stat5 activation plays a pivotal role in nearly all hematological malignancies and occurs downstream of oncogenic kinases, e.g., Bcr-Abl in chronic myeloid leukemias (CML) and Jak2(V617F) in other myeloproliferative diseases (MPD)." (PMID 25809097, 2015). "The Janus kinase 2 (JAK-2)/signal transducers and activators of transcription (STAT) pathway play a key role in the proliferation and pathogenesis of hematologic malignancies." (PMID 22536253, 2012). "Given his positive family history of hematologic disorder requiring phlebotomy and low EPO, he was assessed for Janus kinase-2 (JAK2) V617F and exon 12-15 mutations, which were also negative." (PMID 39280364, 2024).
hematologic malignancies (continued). "Similar to the UK Biobank, co-occurring JAK2 V617F and 9p CN-LOH (n = 100, OR = 5693 q < 0.001) are consistent with the well-known mechanisms of bi-allelic alterations in specific genes driving the pathogenesis of hematologic malignancies." (PMID 38225345, 2024). "Following positive molecular testing for known mutations (JAK-2, CALR2, and MPL), at times followed by a bone marrow biopsy to rule out hematologic malignancy, a treatment protocol can be implemented in order to control the dysfunction of the bone marrow." (PMID 35493844, 2022). "Our data suggest that a combination of JAK2 and PIM inhibitors might warrant further investigation for the treatment of JAK2-driven hematologic malignancies." (PMID 24830942, 2014). "Our data suggest that JAK2 and PIM combination might warrant further investigation for the treatment of JAK2-driven hematologic malignancies." (PMID 24830942, 2014). "The effectiveness of JAK2 inhibition in K562 cells, but not in epithelial tumor cells is probably one of the reasons why JAK2 inhibitors are more widely used in clinical trials of hematological malignancies but not of the epithelial solid tumors." (PMID 25691062, 2015).
infection (73 papers, 2010 to 2026). The state of being infected such as from the introduction of a foreign agent such as serum, vaccine, antigenic substance or organism. "IL-6 is a cytokine with multiple functions that mediate the response to infection or injury and participates in tumourigenesis caused by activation of JAK2/STAT3 signaling." (PMID 39103836, 2024). "The main side effect of inhibitors of JAK1 and JAK2 can be an increased risk of infection, related to a depressed Th1 response and a reduced production of interferon-gamma (INF-γ)." (PMID 39100065, 2024). "The JAK2 46/1 haplotype has also been associated with myelomonocytic phenotype and reduced infection-related survival in normal-karyotype acute myeloid leukemia." (PMID 32967342, 2020). "We also show that JAK2/STAT5 signaling is required for GM-CSF to enhance cytokine expression during infection." (PMID 40470942, 2025). "This process connects interferon-gamma receptor 1 to Janus kinase 2 (JAK2), potentially resulting in the activation of PD-L1, a known immunosuppressive molecule that perpetuates both infection and the wound healing process." (PMID 41271007, 2025). "We did not examine the ruxolitinib pre-infection only condition, as our previous studies showed that ruxolitinib pre-infection treatments are ineffective in PDAC cells due to the rapidly reversible nature of JAK1/JAK2 inhibition by this drug." (PMID 40214229, 2025). "In contrast, treatments with PGE2 or JAK-2 + IFN-γ resulted in significantly higher lesion scores in DMV/1639-infected TOCs compared with the infection-only group." (PMID 39472003, 2024). "In infection by other intracellular bacteria such as Brucella and Mycobacterium, the JAK2/STAT3 pathway is important for the intracellular growth and pathogenesis." (PMID 39255287, 2024). "Treatment with IFN-γ, SC-236, PGE2 receptor inhibitors, or JAK inhibitors reduced IBV infection and lesion scores, whereas exogenous PGE2 or IFN-γ pretreatment with a JAK-2 inhibitor augmented infection." (PMID 39472003, 2024). "We further discovered that B7-H4−/− infection impairs the JAK2/STAT3 pathway, contributing to dDC dysfunction." (PMID 35505420, 2022). "Nicotine (α7nAChR agonist) aggravated E. coli-induced BBB injuries, while MLA and MEM (α7nAChR antagonist) exhibited protective effects by regulating the α7nAChR/CISH/JAK2/STAT5 signaling pathways during infection." (PMID 36289622, 2022). "A recent report indicated that G-CSF is known to activate the phosphorylation of STAT3 via JAK2 and is involved in the maintenance of normal circulating granulocyte counts and in the neutrophilic response during infection." (PMID 34356683, 2021). "We isolated and imaged platelets from mice with either somatic mutations in JAK2, JAK2V617F, that cause MPNs or platelets from mice with experimental VL following infection with L. donovani." (PMID 33041864, 2020). "Our findings confirmed that PRRSV-1 interferes with the JAK-STAT signaling in NPTr cells, by downregulating the phosphorylation of JAK2 and leading to the low expression of ISGs even after swIAV infection." (PMID 32899579, 2020). "Our previous studies showed that treatment with ruxolitinib (a JAK1/JAK2 inhibitor) enhances VSV-ΔM51 replication in cell lines with functional type I IFN signaling but only when ruxolitinib was present after infection." (PMID 30487274, 2019). "Leptin signal sensitivity was significantly altered after leptin vectors infection as represented by the change of phosphorylation of JAK2 and STAT3." (PMID 29250056, 2017). "E. chaffeensis blocks tyrosine phosphorylation of Stat1, Jak1, and Jak2 in response to IFN-γ through raising PKA activity in THP-1 cells soon after infection." (PMID 27303657, 2016). "In contrast, the LPCAT2 activation values were reduced to 35.65 % at 5 min post-infection in JAK2-inhibited cells." (PMID 27098179, 2016).
infection (continued). "MAPK pathways, both ERK1/2 and p38, showed phosphorylations after 5 min of contact with the virus while phosphorylation-mediated activation of JAK2 appeared between 30 and 60 min post-infection." (PMID 24712747, 2014). "IL-6 inducible negative regulator of Janus kinase 2 (Jak2), suppressor of cytokine signalling 1 (Socs1), was upregulated late following infection, at day 6 pi." (PMID 22679491, 2012). "Given that STAT1 and JAK2 were significantly downregulated in infected cells in ADE compared to conventional infection conditions, it is possible that in ADE-mediated infection, these interactions are differentially modulated such that they further enhance viral evasion strategies." (PMID 39902963, 2025). "Western blotting revealed that PmA infection indeed activated the Jak2–Stat3 pathway in vivo, suggesting that the IL-6–JAK2–Stat3 axis may be involved in the development of Th17 cells during PmA infection." (PMID 41402924, 2025). "Using cervical epithelial HEp2 cells that were validated to respond homogeneously to physiologically relevant levels of IFNγ, we observed reduced expression and activation of both STAT1 and its kinase JAK2 at early stages of infection, with concomitant reduction in expression of ISGs." (PMID 39194253, 2024). "Therefore, inhibitors such as cucurbitacin I and Stattic can be utilized as antimicrobial agents, and the JAK2/STAT3 pathway can be a therapeutic target of infection with intracellular bacteria as well." (PMID 39255287, 2024). "Thus, the JAK2/STAT3 pathway is important for the infection and pathogenesis of various bacterial intracellular infections." (PMID 39255287, 2024). "The expression of STAT1, JAK1, and JAK2 genes increased following the infection time." (PMID 33240261, 2020). "In addition to activation of JAK2 and STAT3 by KSHV de novo infection, the JAK2 and STAT3 activating cell surface receptor gp130 is induced by KSHV infection." (PMID 33182552, 2020). "Activation of STAT3 is mediated by JAK2 upon KSHV de novo infection." (PMID 33182552, 2020). "Thus, this sequential processing and correlation implies that B. abortus utilizes a supporting mechanism (non-binding membrane receptor PAFR), which modulates the activation of PAFR-mediated JAK2 signaling pathway during the entry step of infection." (PMID 27098179, 2016). "Consistently, the JAK2 GGCC haplotype was reported to be associated with a defective response to cytokine stimulation, increased risk of inflammation, and impaired defense against infection." (PMID 26538820, 2015). "Situations where chronic inflammation results from more than one cause are not rare: physical injury and infection, thrombosis and hypoxia, solid cancer and infection, JAK2-mutated MPN and thrombosis, and so forth." (PMID 26538820, 2015). "Similarly, expression of several genes in the canonical IFN signaling pathway, including Ifng, Jak2, Stat1, Stat2, Socs1, Irf1, Irf9, Tap1, Ifitm1, Psmb8, Ifi35, Gas1 and Fit3 were up-regulated during infection by the mutant strain." (PMID 25201772, 2014). "Interestingly, mouse microarray data showed Jak2, Stat1 and Stat3 as vital proteins in this pathway and were up-regulated at the 4 days post-infection." (PMID 21172007, 2010). "Top downregulated DEGs in bystander cells indicated a decreased enrichment of certain pro-inflammatory cytokines and signaling molecules in ADE compared to conventional infection conditions, including CXCL11, CXCL10, CCL2, DOCK4, STAT1, and JAK2." (PMID 39902963, 2025). "We observed an infection-dependent decrease in STAT1 transcript as early as 8 to 16 hpi in infected cells and a decrease in JAK2 between 16 and 24 hpi." (PMID 39194253, 2024). "Our results showing lower JAK2 and STAT1 expression levels during infection prompted us to determine if this required chlamydial protein synthesis." (PMID 39194253, 2024).
infection (continued). "In TFs-mRNA network, JAK2 and STAT2 mediate the signal transduction of more than 50 cytokines and growth factors in many different cell types, which is critical for resisting infection and enforcing barrier functions." (PMID 36969251, 2023). "Meanwhile, cells-treated with 300 μg/mL arginine medium ruduced the phosphorylation and gray values of p-JAK2 and p-STAT3 after infection with FAdV-4, compared with FAdV-4 infection cells (P < 0.05)." (PMID 35590365, 2022). "The p‐JAK2/JAK2 and p‐STAT1/STAT1 ratio reached highest level at 10 days post‐infection and decreased at 20 days post‐infection." (PMID 33959966, 2021). "AKT, AMPK, and JAK2 phosphorylations were decreased in the presence of live PRRSV-1 at 5 and 10 min post-infection (mpi)." (PMID 32899579, 2020). "It has been elucidated that JAK2 is involved in the activation of Src-kinase, PI3K, MAPKs, and STAT downstream signaling following cytokine receptor activation and infection." (PMID 27098179, 2016). "The present study showed that integrin β1 mediates HGPg infection-induced SREBP-1c and NLRP3 expression through the activation of JAK2 and phosphorylation of Akt and p70S6K." (PMID 28083517, 2016). "Following infection, SET2 cells were selected with puromycin for three days and re-plated at low density before initiating treatment with DMSO or JAK2 inhibitor at 0.2 and 0.35 μM, which are the IC25 and IC50 of SAR302503, respectively." (PMID 24830942, 2014). "In contrast to infection with live HCMV, decreased activation of STAT3 and JAK2 was observed in cells treated with UV-inactivated HCMV." (PMID 23555719, 2013). "They further revealed that upon infection, PTP SHP-1 is also rapidly induced, which interacts strongly with JAK2, and impairs IFN-γ signaling." (PMID 22091401, 2011). "Analysis of differentially expressed genes in the LC group compared with the CC group at day 90–180 after infection identified an increase of multiple proinflammatory markers, such as IL6, NLRP3, TNF, JAK2, CSF2, IL1B and IL10, in the LC compared with the CC group." (PMID 41388153, 2026). "We were able to confirm that JAK2 protein was also decreased during infection compared with uninfected cells, but we were not able to detect JAK1 protein under any conditions by immunoblotting (data not shown)." (PMID 39194253, 2024). "Indeed, astrocytes showed significant increases in JAK2, STAT3, and phosphorylated counterparts after gp120 infection." (PMID 36997969, 2023). "However, treatment with AG490, a selective inhibitor of JAK2, only marginally reduced STAT3 phosphorylation levels upon M81 infection." (PMID 37830871, 2023). "In the ileal network, JAK2 and CREB1, as well as SMAD2, SMAD3 and ERK2 (MAPK1) seem to play a central role in the intracellular PPI signalling driven by viral miRNAs and viral proteins, respectively, and JAK2 and both SMAD2 and SMAD3 were also upregulated upon infection." (PMID 35501398, 2022). "While JAK1 shows only marginal expression in A549 cells, there was a clear activation of JAK2 (phosphorylation of JAK2 at Y1007/Y1008) and its downstream target signal transducer and activator of transcription 3 (STAT3, phosphorylation at Y705) detectable upon WSN infection." (PMID 32866218, 2020). "JAK1, JAK2, JAK3, and Tyk2 all became more phosphorylated after infection of ST cells by TGEV." (PMID 28642467, 2017). "TRP120 and Ank200 target genes of important components of the Jak-Stat pathway, e.g., Jak2, Stat1, Stat3, Stat5, and IFNR2, and thus might be involved in regulation of IFN-γ signaling during infection." (PMID 27303657, 2016). "However, JAK2 and JAK3 appeared to be targets for dephosphorylation where both had a three-fold decrease in phosphorylation at four days post-infection." (PMID 27472318, 2016).
infection (continued). "Genetically deficient BMDMs in CCR5 (CCR5-/-) or treatment with specific inhibitors to JAK2 (Tyrphostin AG490), NF-κB (CAPE), AP-1 (Tanshinone) or mTOR (Rapamycin) did not yield significant differences in cytokine production after infection, if compared to WT or untreated controls." (PMID 27679624, 2016). "Infection triggered tyrosine phosphorylation of both JAK1 and JAK2, in addition to STAT3." (PMID 21931552, 2011). "Although there is a significant increase in transcript levels of the known JAK-STAT negative regulator SOCS3 during infection, which can lead to JAK2 protein degradation, this does not explain the decrease in levels of both JAK2 and STAT1 at the transcript level." (PMID 39194253, 2024). "Using an overexpression experiment, Fung showed that JNK/MAPK8 participated in coronavirus–host interaction, so silencing lncRNA−MSTRG.16919.1 may affect the expression of SKIV2L2, JAK2, PIK3CB and MAPK8 proteins and then regulate the infection of MDBK cells by BHV−1." (PMID 36298658, 2022). "Surprisingly, in our study we also observed that more than 18 key genes, including Jak2, Stat3, Stat5a, Pik3r5 and Cish, of JAK-STAT pathway were significantly up-regulated by S. aureus + PG infection, thus indicating that S. aureus + PG treatment might also activate JAK-STAT signaling." (PMID 29304086, 2018). "Furthermore, the correlation between diverse lymphocyte and myeloid populations and other DE-CRs (JAK2 and SP140) suggests that epigenetic modulation plays a more extensive role in determining the identity, recruitment, and functional capacity of immune cells during infection." (PMID 41290882, 2025). "Cucurbitacin I or Stattic treatment after infection failed to decrease the number of intracellular F. novicida, indicating that intracellular proliferation was not affected by the inhibitors, indicating that the JAK2/STAT3 pathway is important for the internalization step of F. novicida." (PMID 39255287, 2024). "As expected, we also observed that ASFV-Δ7R infection elevated the JAK1, JAK2, and Hes5 expression level in PAM cells, but not the RNF125 and ASFV p30 expression level in comparison with those of parental ASFV-infected cells." (PMID 34517008, 2021). "However, some genes, such as Jak2, Notch2, and Runx1, were up-regulated in KRAS+ mice regardless of infection status." (PMID 33310760, 2021). "Importantly, basal JAK2 and STAT1 transcript and protein levels were dampened by infection even in the absence of interferon, which could have implications for cytokine signaling beyond IFNγ." (PMID 39194253, 2024). "Additionally, SOCS proteins that can downregulate JAK and STAT1 phosphorylation are actually induced by Toxoplasma infection, and the expression of the protein tyrosine phosphatases (PTPs) that are known to dephosphorylate JAK1, JAK2, or STAT1 are not downregulated by infection alone." (PMID 23240025, 2012).